EGFR (epidermal growth factor receptor)
Diseases named in the same sentence as EGFR in open-access papers (continued):
Sharing a sentence is not in itself a finding about the gene and the disease.
asthma (continued). "Several studies have shown that EGFR is overexpressed in the airway epithelium of asthmatic patients and animal models of asthma, leading to increased airway inflammation, airway hyperresponsiveness, and airway remodeling." (PMID 38178132, 2024). "Baicalein attenuates airway inflammation and airway remodeling through inhibition of VEGF and EGFR signaling pathways in an OVA-induced asthma mouse model." (PMID 38178132, 2024). "Epidermal growth factor receptor (EGFR) is another important modulator of mucin expression that is activated in asthma." (PMID 36684665, 2023). "Dysregulation of the EGFR pathway causes aberrant EGFR signaling, which is associated with the early-stage pathogenesis of respiratory diseases, such as cancer, lung fibrosis, COPD, asthma, and cystic fibrosis." (PMID 35466228, 2022). "Methyl rosmarinate (degree, 8; betweenness centrality, 0.02733; closeness centrality, 0.4715) also shared the same targets (STAT3, PIK3CB, MAPK1, ESR1, SYK, and EGFR) and identical asthma-related signaling pathways with caffeic acid." (PMID 35572723, 2022). "Asthma patients express more EGFR in the airway epithelium and it has stronger functions than those observed in healthy people." (PMID 36699060, 2022). "EGFR expression was found to be increased in airway epithelial cells of asthmatic patients, especially those with severe asthma." (PMID 36618942, 2022). "Allergic inflammation in murine asthma model is reported to be regulated by SRC transactivation of EGFR, followed by activation of ERK1/2/NFκB32." (PMID 36163190, 2022). "PDGFRs, such as EGFR, are key players in chronic tissue remodeling in asthma, bronchitis and pulmonary fibrosis." (PMID 36146864, 2022). "The signaling pathways enriched for asthma in the KEGG pathway analysis included the EGFR tyrosine kinase inhibitor resistance, Jak-STAT, PI3K-Akt, and Fc epsilon RI signaling pathways." (PMID 35572723, 2022). "AREG was found to lead to the proliferation of airway epithelial cells and airway smooth muscle cells through EGFR activation, thereby affecting airway remodeling in severe asthma." (PMID 36578010, 2022). "We suggest that one of the mechanisms by which GSZC granules improve airway inflammation is intervention in the MUC5AC/EGFR signaling pathway, and inhibition of mucus hypersecretion in the airways of rats suffering from asthma." (PMID 36699060, 2022). "The EGFR is expressed only in the bronchial epithelium and glands in normal airways, but EGFR expression is seen in the bronchial smooth muscle and basement membrane of patients suffering from asthma." (PMID 36699060, 2022). "EGFR was observed to be highly expressed in bronchial epithelial cells in asthma and the ErbB signaling pathway (FDR = 1.88 × 10−4) plays a key role in mediating airway hyperresponsiveness and remodeling in a chronic allergic mouse model." (PMID 33923455, 2021). "Both oxidative deactivation of protein tyrosine phosphatases and cysteine oxidation of the EGFR structural domain activate and enhance EGFR signaling, thereby exacerbating the course of asthma." (PMID 34564383, 2021). "UPM exposure decreased the proportion of EGFR + epithelial cells in all evaluated groups with significant changes found in asthma epithelial cells with ciliated phenotype (50.3% (27.7–60.7%) versus 25.2% (18.3–37.9%), p = 0.049)." (PMID 34168212, 2021). "There is translational evidence indicating upregulated expression of EGFR appears in the airways of asthmatics and activity of this signaling pathway is enhanced in relation to asthma severity." (PMID 33195308, 2020). "In conclusion, our data clearly show that OBE inhibits the asthma phenotype in a clinically relevant murine model of asthma, at least in part, via inhibition of Th2 cytokine profile, via inhibition of the EGFR/ERK/1/2/AKT signaling pathway." (PMID 33123005, 2020).
asthma (continued). "Others have reported a strong correlation between EGFR expression and neutrophilic-specific chemokines in the epithelium of patients with severe asthma." (PMID 33195308, 2020). "Many asthma triggers like allergens, viruses, and pollutants activate EGFR signaling, which seems to be a common pathway shared by different asthma phenotypes." (PMID 33195308, 2020). "That OBE can inhibit the EGFR-triggered signaling perturbations suggests that it can inhibit a central signaling pathway in asthma." (PMID 33123005, 2020). "More importantly, a positive correlation between EGFR immunoreactivity and MUC5AC mucin staining was noted when bronchial biopsies from healthy volunteers and subjects with mild-to-moderate asthma were compared, suggesting a causal relationship." (PMID 33123005, 2020). "There are extensive studies focusing on the relation between EGFR and asthma pathophysiology, which describe airway remodeling, airway hypermucus secretion, as well as immunological responses of airway inflammation." (PMID 33217964, 2020). "Activated EGFR has also been shown to be associated with mucin gene expression, and expressed in the airways of seasonal allergic rhinitis, COPD, cystic fibrosis, asthma, as well as CRSwNP patients." (PMID 32514271, 2020). "EGFR is also activated by bacterial components of lipopolysaccharide (LPS), which is often used as bacterial-induced asthma exacerbation model." (PMID 33217964, 2020). "Specifically mucus hypersecretion is induced by EGFR activation to promote goblet-cell metaplasia in severe asthma." (PMID 33195308, 2020). "Further studies will be needed to elucidate the clinical implications of EGFR expression in patients with the severe asthma phenotype." (PMID 33217964, 2020). "This defect was due to abnormal phosphorylation of epidermal growth factor receptor (EGFR) in the mild asthmatic-airway epithelium due to increased release of the activated form of TGF-β1 by asthma-derived airway fibroblasts." (PMID 32679790, 2020). "The major finding of this study is that OBE produces anti-inflammatory actions in an established asthma model, partly, via inhibition of the EGFR/ERK1/2/AKT pathway." (PMID 33123005, 2020). "They reported that EGFR expression in airway epithelial cells increased in asthma, more prominent in severe asthmatic airway epithelium." (PMID 33217964, 2020). "This study therefore shows that inhibition of the EGFR/ERK1/2/AKT-dependent signaling pathway is one of the key mechanisms by which OBE can mediate its anti-inflammatory effects in diseases such as asthma." (PMID 33123005, 2020). "Cells such as epithelial cells, macrophages, and T cells and signal pathways like the nuclear factor-κB signaling pathway and the EGFR-PI3Kα-AKT/ERK pathway were also reported to be involved in the incidence of asthma." (PMID 32411804, 2020). "An ex vivo study using bronchial specimens from childhood asthma showed that airway EGFR expression increased more in severe childhood asthmatics than control or moderate asthmatics." (PMID 33217964, 2020). "Along with transcriptomic analysis among cohorts, including severe asthma patients, the EGFR pathway makes considerable contributions to mucus metaplasia among asthmatics, as well as the IL-13 pathway." (PMID 33217964, 2020). "EGFR also involves interaction with eosinophils, which are important for eosinophilic airway inflammation observed in a severe asthma phenotype." (PMID 33217964, 2020). "In animal models of asthma, selective EGFR inhibitors such as AG1478 and gefitinib, significantly reduced airway smooth muscle hyperplasia/remodeling, eosinophil recruitment, inflammation, AHR and epithelial and goblet cell proliferation." (PMID 31675376, 2019). "In contrast, the expression of EGFR is decreased both in dust mite-induced asthma patients and HBE transfected with miRNA-27b-3p plasmid, which is not we have expected." (PMID 30406061, 2018).
asthma (continued). "Meanwhile, SYK and EGFR were taken grant for modulating the progress of asthma by function in PI3K pathway and influence on cell differentiation, T or B cell and so on." (PMID 30406061, 2018). "Inhibition of EGFR signaling can decrease the inflammation and airway responses in mouse models of asthma." (PMID 30005089, 2018). "Meanwhile, it also has been shown that EGFR (Epidermal growth factor receptor) can regulate the inflammation pathway in pulmonology allergy disease and asthma." (PMID 30406061, 2018). "To further understand the mechanism(s) by which EGF/EGFR is involved in inducing inflammatory cell influx in the asthma phenotype, we examined the direct and indirect effects of EGF/EGFR signaling on mononuclear and neutrophil chemotaxis in vitro." (PMID 28855674, 2017). "Our data showed that increased EGFR mRNA and protein expression as well as phosphorylation of EGFR resulted in several of the pathophysiological features of asthma." (PMID 28855674, 2017). "The interplay between SFK and EGFR and the exact context of the Src/EGFR signaling pathway in the pathogenesis of asthma is poorly understood." (PMID 28855674, 2017). "The results were consistent with suggested use of antagonists of A1AR, calcium-activated chloride channel regulator 1 (CLCA1), and epidermal growth factor receptor (EGFR) in asthma treatment." (PMID 29311944, 2017). "More importantly, we show that inhibition of the SFK, with SU6656, inhibited EGFR phosphorylation and its associated downstream signaling which suggests that SFK is an important mediator of EGFR transactivation in this model of asthma." (PMID 28855674, 2017). "In asthma, EGFR expression is increased in the epithelium and activation of EGFR contributes to airway epithelial repair." (PMID 27285994, 2016). "TACE/EGFR signaling also regulates mucin production in epithelial cells, which contributes to exacerbation of asthma, COPD, and cystic fibrosis." (PMID 26147224, 2015). "EGF/EGFR has a role to play in the disequilibrium of the bronchial epithelium in asthma and is considered a promising target for pharmacotherapy." (PMID 26057128, 2015). "This further highlights the epidermal growth factor receptor as a potential therapeutic target to inhibit goblet cell hyperplasia and mucus hypersecretion in asthma." (PMID 26057128, 2015). "For example, thioredoxin (TRX) reduces gene expression of TGF-β1, EGFR, and p21 to influence airway epithelia and prevent airway remodeling in a asthma mouse model." (PMID 24167583, 2013). "It has also been reported that EGFR plays an important role in the pathogenesis of asthma and inhibitors of tyrosine kinase have been studied as a novel therapeutic strategy for the treatment of asthma." (PMID 22132240, 2011). "Altered expression of CD44 as well elements of TGF-β and EGFR signaling play a role in airway remodeling in asthma." (PMID 21572528, 2011). "The EGFR has been shown to be of importance in these principal functions, as highlighted in respiratory diseases such as asthma, the most common condition recognised to be affected by particulate air pollution." (PMID 18460189, 2008). "Moreover, IFNG is critical for regulating asthma airway hyperreactivity, and EGFR can affect distal airway epithelial responses to allergies and manage airway epithelial inflammation." (PMID 40420184, 2025). "Increased EGFR expression is consistent with other reports in asthma and may contribute to airway remodeling if chronically activated." (PMID 40791985, 2025). "We suggest that airway inflammation is particularly prominent in patients with severe asthma and that the upregulation of EGFR may be a response to inflammatory mediators such as cytokines." (PMID 40160461, 2025). "The role of EGFR inhibitors in asthma treatment has been investigated in several studies." (PMID 38178132, 2024).
asthma (continued). "Our findings support a role for enhanced EGFR signalling in asthma airway remodelling and might suggest a functional involvement of ERBB2, also known as human epidermal growth factor receptor 2 (HER2), and ERBB4, also known as HER4, in its pathogenesis." (PMID 39401856, 2024). "Specifically, only EGFR (epithelial growth factor receptor) and SMAD genes, both of which are associated with epithelial dysfunction and AR, were upregulated in children whose viral upper respiratory infections progressed to asthma exacerbations." (PMID 38981012, 2024). "Moreover, targeted anti-eosinophilic treatment with anti-IL5 antibody in children with moderate-to-severe asthma who had an increased EGFR/SMAD-related nasal epithelial/remodeling gene signature resulted in worsening exacerbations." (PMID 38981012, 2024). "Asthma appears to be more common in patients with EGFR mutations than in those without mutations (50% vs. 6.8%, p = 0.014), but this result is recommended to be interpreted with caution given the small number of cases." (PMID 39199673, 2024). "A previous study found that the expression level of EGFR in bronchial epithelial cells was increased in asthma and correlated with disease severity and that the activation of EGFR signaling in airway epithelial cells contributed to mucus metaplasia in a chronic asthma model." (PMID 36575422, 2022). "EGFR expression was positively correlated with the severity of asthma." (PMID 36578010, 2022). "We can speculate that air pollution contributes to airway remodeling through EGFR or ST2 on ciliated cells in asthma patients." (PMID 34168212, 2021). "The highest proportion of EGFR + epithelial cells was noted in asthma patients." (PMID 34168212, 2021). "As EGFR protein levels are increased in severe asthma, it would be of interest to study EGFR protein expression in the U‐BIOPRED cohort and to determine whether post‐translational mechanisms are also important for EGFR regulation." (PMID 32096290, 2020). "The epidermal growth factor receptor (EGFR) signaling is vital to epithelial cell physiology, and its dysregulation is involved in different pathologies, including pathogenesis of early stage of asthma." (PMID 33195308, 2020). "Thus, increased EGFR expression is a consistent finding not only in asthma but across several disease states." (PMID 33123005, 2020). "In addition, ERK1/2 and AKT are not only key signaling molecules in asthma but have also been recently shown to be downstream of EGFR activation." (PMID 33123005, 2020). "In biopsy specimens from severe asthmatics, EGFR expression and neutrophils increased when compared to mild asthma, and EGFR expression was positively correlated with IL-8 expression, suggesting that EGFR contributes to sustained neutrophilic airway inflammation." (PMID 33217964, 2020). "Specific inhibition of EGFR activation may be a potential therapeutic target for chronic airway inflammatory disease including asthma." (PMID 33217964, 2020). "A study using an OVA-induced asthma mice model showed that the treatment with EGFR or Src inhibitor improved allergic airway inflammation represented as inflammatory cells in broncho alveolar lavage fluid (BALF), peribronchial inflammation, airway remodeling, and AHR in the same degree." (PMID 33217964, 2020). "Also, areas of epithelial damage in asthmatic patients exhibited a strong EGFR immunoreactivity suggesting that EGFR activation plays an important role in the epithelial damage/repair process in asthma." (PMID 33123005, 2020). "One possible mechanism underlying aggravation of asthma by SO2 could be that SO2 derivatives increase the expression levels of EGF, EGFR, ICAM-1, and COX-2 proteins in BEP2D cells." (PMID 30885130, 2019). "A growing body of evidence shows that EGFR-dependent signaling plays a significant role in asthma." (PMID 31675376, 2019).
asthma (continued). "The importance of EGFR signaling has also been noted in chronic obstructive pulmonary disease (COPD) where EGFR activity is increased and is associated with mucosal cell metaplasia—an important pathophysiological feature in both asthma and COPD." (PMID 31675376, 2019). "The development of stable long acting MAS1 agonists may be a more effective alternative to EGFR inhibitors as potential anti-inflammatory therapy for asthma and other diseases." (PMID 31675376, 2019). "Indeed, we have recently shown that ERK1/2, in addition to PI3K/AKT, is an important signaling effector molecule downstream of EGFR and its selective blockade results in reduction of the asthma phenotype." (PMID 31675376, 2019). "According to the rule of miRNA regulating targeted mRNA, in which targeted mRNA can be regulated by multiple miRNAs, we propose that EGFR may be co-regulated by other miRNAs in dust mite-induced asthma." (PMID 30406061, 2018). "This suggests that miRNA-27b-3p may have a regulatory function involved in the degradation or inhibition of SYK and EGFR in the asthma group(s)." (PMID 30406061, 2018). "To confirm the role of EGFR in our murine model of asthma, we firstly determined the expression and phosphorylation level of EGFR protein by immunohistochemistry, immunofluorescence and EGFR mRNA by RT-PCR in lung tissue from different treatment groups challenged with either OVA or PBS." (PMID 28855674, 2017). "Whilst the importance of these signaling pathways is recognized in asthma, what remain unclear is whether they are downstream of EGFR and/or Src and their relative contribution in regulating the asthma pathobiology." (PMID 28855674, 2017). "Furthermore, a broader upstream inhibition of Src/EGFR offers an attractive therapeutic alternative in the treatment of asthma relative to selectively targeting the individual downstream signaling effectors." (PMID 28855674, 2017). "In conclusion, the data presented in this study show that, in a murine asthma model, Src-kinase mediates EGFR transactivation which in turn stimulates multiple downstream signaling pathways involving ERK1/2 and PI3Kδ and transcriptional factor NFκB to regulate allergic lung inflammation." (PMID 28855674, 2017). "Taken together with previous publications showing a key role of LL-37 in immunomodulation, our findings elucidated a mechanism by which LL-37 could induce the accentuation of asthma through P2X7/EGFR and innate immunity." (PMID 28500314, 2017). "Our finding that Src is an important transactivator of EGFR in asthma, therefore leads us to speculate that SFK may be a signaling hub and relay transducing pathways that could lead to airways inflammation, remodeling and AHR." (PMID 28855674, 2017). "However, BALF from OVA challenged mice induced significant eosinophil and neutrophil chemotaxis which was blocked by EGFR inhibition implying that EGFR regulates chemotaxis of two important inflammatory cells in asthma pathogenesis by indirect mechanisms." (PMID 28855674, 2017). "Interestingly, amphiregulin is an epidermal growth factor receptor (EGFR) ligand that has been linked to the regulation of tissue repair and remodeling in the context of acute asthma attacks and epithelial injury." (PMID 26965110, 2016). "This adds further strength to the possibility that targeting EGFR may be a potential therapeutic for airway remodelling, a current unmet need in asthma treatment." (PMID 26057128, 2015). "Evidence of epigenetic regulation of EGFR has significant implications in the setting of asthma given its role in epithelial functions such as differentiation and proliferation and may provide a novel therapeutic modality in this disease." (PMID 26243279, 2015). "Our finding of increased association of acetylated H3K18 upstream of the EGFR TSS in AECs from asthmatics indicates that histone acetylation may be an epigenetic regulatory component of epithelial EGFR overexpression observed in asthma." (PMID 26243279, 2015).